CDK4 (cyclin dependent kinase 4)
Diseases named in the same sentence as CDK4 in open-access papers (continued):
Sharing a sentence is not in itself a finding about the gene and the disease.
tumor (continued). "The same study demonstrated anti-tumor effects of CDK4/6 inhibitors in CDK4-gain AM cell lines and patient-derived xenograft mouse models." (PMID 39858514, 2025). "Although CDK4/6 degraders show encouraging anti-tumor efficacy, it is highly desired to develop strategies to spatiotemporally control the release of active CDK4/6 degraders to further reduce adverse effects." (PMID 40894871, 2025). "De-repression of NFAT by palbociclib or another CDK4/6 inhibitor, trilaciclib led to T cell activation and synergized with immune checkpoint inhibitors in an organotypic tumor spheroid culture model and in syngeneic tumors in mice." (PMID 40699853, 2025). "At the mechanistic level, CDK4/6 inhibitors up-regulated in tumour cells the expression of PD-L1, which is an established biomarker for ICI responsiveness in certain tumours." (PMID 41388212, 2025). "Immunohistochemical analysis suggested MDM2, CDK4, and P16 positivity in tumor cells, with MDM2 amplification confirmed in the mucinous area." (PMID 40826716, 2025). "In clinical settings, it was also found that high KIFC2 mRNA expression was associated with tumor growth and poor survival of patients with HR+/HER2– BC who received ET alone or in combination with CDK4/6 inhibitors." (PMID 40299549, 2025). "CDK4/6is can effectively enhance immunogenicity depending on the fact of CDK4/6is inducing ICD in tumor cells." (PMID 41463246, 2025). "Combining CDK4/6 inhibitors with endocrine therapies enhances therapeutic efficacy by downregulating cyclin D1 expression, thereby reducing CDK4/6 complex formation and inhibiting tumor growth." (PMID 41331382, 2025). "Both MDM2 (a murine double-minute gene indicator) and CDK4 (cyclin-dependent kinase 4) were expressed in the tumor cells." (PMID 40926903, 2025). "Researchers utilized novel LNPs to encapsulate nucleic acid drugs, significantly downregulating the cyclin-dependent kinase 4 (CDK4) gene in tumor cells and thereby regulating tumor cell proliferation." (PMID 39796233, 2025). "Recent work has shown that targeting CDK4/6-mediated checkpoints restores this negative regulatory control and enhances anti-tumor immunity in NSCLC, offering a promising therapeutic strategy." (PMID 41228248, 2025). "Interest has grown in understanding the role of CDK4/6 inhibitors beyond their impact on tumor cell proliferation." (PMID 40341398, 2025). "CDK4/6i have been proposed to establish a tumor‐specific memory CD8+ T‐cell pool, thereby allowing for subsequent administration of immune checkpoint blockade." (PMID 40936164, 2025). "This review aimed to investigate recent preclinical studies on the role of CDK4/6is in tumor immunity." (PMID 41463246, 2025). "An increasing number of studies have shown that CDK4/6 inhibitors not only act on the cell cycle but also have an impact on tumor immunity." (PMID 41463246, 2025). "This work demonstrates that XPO1 inhibitor KPT‐330 in combination with CDK4/6 inhibitor additively suppressed BLBC tumor growth in vivo." (PMID 39888288, 2025). "Understanding the SASPs triggered by various CDK4/6is will help to fully utilize the anti-tumor and immune-stimulating properties of senescence to treat tumors or develop better combined treatment strategies." (PMID 41463246, 2025). "We further demonstrated that combined inhibition of NEK6 and CDK4/6 resulted in marked suppression of tumor growth in vitro and in vivo." (PMID 41560755, 2025). "ecDNA amplifications that harbor driver oncogenes such as EGFR, MYC, MDM2, and CDK4 were detected in 17.1% of 39 human tumor subtypes, including GBM24." (PMID 40678238, 2025). "When tested in AM cell lines and xenograft models, CDK4/6 inhibitors demonstrated preclinical anti-tumor effects, targeting aberrant cell proliferation." (PMID 39858514, 2025). "This is one of the mechanisms by which CDK4/6‐mediated dysregulation of the tumour cell cycle results in uncontrolled tumour cell proliferation." (PMID 40525649, 2025).
tumor (continued). "Similar to aSCLC, CCND1, CDK4, and MDM2 are among the most common amplifications associated with chromothripsis across tumor type." (PMID 39185963, 2025). "Previous evidences showed that CDK4/6i induce cell cycle arrest, and they can affect the differentiation of non-tumor cells, such as osteoclasts." (PMID 40424680, 2025). "This reciprocal resistance underscores the therapeutic rationale for combining CDK4/6 inhibitors with upstream kinase inhibitors tailored to tumor-specific signaling aberrations." (PMID 40421216, 2025). "This has led to the exploration of combinatorial strategies that restore RB activation or prevent its phosphorylation in an effort to enhance the sensitivity of tumor cells to CDK4/6 inhibitors and suppress their proliferative capacity." (PMID 41326426, 2025). "The primary mechanism of action of CDK4/6 inhibitors in anti-tumor activity is to induce cell cycle arrest." (PMID 40468178, 2025). "Worthy, CDK4/6 inhibitors have shown the ability to orchestrate anti-tumour immunity and long-term anti-tumour effects, leading to immunogenic cell death (ICD)." (PMID 41388212, 2025). "Preclinical studies indicate that CDK4/6 inhibition can increase tumor cell MHC class I expression and augment T-cell activation, while also reducing regulatory T-cell infiltration in certain models, thereby enhancing cytotoxic T-cell–mediated immunity." (PMID 41280894, 2025). "This panel of genes includes trefoil factor family proteins, TFF1 and TFF3, which have been shown to be upregulated in BL immunohistochemistry tumor samples from patients with HR+/HER2- mBC who experience late progression on CDK4/6i therapy." (PMID 39955556, 2025). "After this period, however, a similar tumor growth rate and an equivalent tumor volume at sacrifice were observed between the CDK4-KO and WT groups (Sup." (PMID 39788939, 2025). "CDK4/6 inhibitors combat malignant tumors by regulating cell cycle, changing tumor microenvironment, triggering antitumor immunity and other mechanisms." (PMID 40421216, 2025). "Recent in vitro studies have shown that CDK4/6 inhibitors can suppress tumor cell growth by enhancing interferon signaling pathways and the presentation of tumor antigens." (PMID 40904706, 2025). "This underscores the need for clinical trials to consider overall survival and tumor progression rates as more appropriate endpoints for assessing the true benefits of sustained CDK4/6i therapy." (PMID 39605351, 2025). "To investigate potential enhancements in treatment efficacy for HR-positive HER2-positive BC, we conducted in vitro studies assessing the impact of CDK4/6 inhibitors combined with HER2-targeted therapy on tumor cell behavior." (PMID 40687942, 2025). "CDK4/6 inhibition demonstrates strong tumor‐suppressive effects with tolerable toxicity by inhibiting RB phosphorylation, preventing E2F release, and blocking the progression from G1 to S phase." (PMID 39968498, 2025). "Altogether, apart from its CDK4/6-dependent activity, abemaciclib can lower B7-H4 protein levels, thereby boosting tumor immunity and preventing tumor progression." (PMID 40341398, 2025). "Preclinical studies demonstrate CDK4/6 knockout selectively inhibits tumor growth while sparing normal cells, underscoring its therapeutic potential." (PMID 40421216, 2025). "Intracellular signalling regulation is intrinsically complex, and tumour cells frequently develop resistance to CDK4/6 inhibitors through compensatory activation of alternative proliferative pathways." (PMID 40563591, 2025). "In another study, tumor and blood samples were collected before initiating combined CDK4/6is and ET, as well as at disease progression." (PMID 40244377, 2025). "While JQ1 improves tumor response to CDK4/6i, BET protein inhibitors have broad ranging effects on gene expression and this has limited their clinical development." (PMID 39826695, 2025). "This review summarized the preclinical and clinical trials results of CDK4/6 inhibitors on tumor immunity." (PMID 41463246, 2025).
tumor (continued). "Emerging therapies targeting the tumor microenvironment and epigenetic dysregulation, including immunotherapies and CDK4/6 inhibitors, hold promise for improving outcomes in this aggressive subtype." (PMID 39877469, 2025). "Specifically, CDK4/6 inhibitors not only suppress tumor cell proliferation but also induce T cell-mediated inflammatory responses, enhance antigen presentation, and upregulate PD-L1 expression." (PMID 41331376, 2025). "Alternatively, an increased migration rate immediately after grafting the CDK4 KO cells would result in a decreased tumor growth in the implantation site." (PMID 39788939, 2025). "Clinical studies have shown that when CDK4/6 inhibitors are used alone, some tumor cells can evade the inhibitory effects of the drugs by activating the PI3K/AKT/mTOR pathway, leading to the development of drug resistance." (PMID 41280894, 2025). "Here, high stromal CDK4 levels in primary tumors were correlated with improved survival, while a significant increase in CDK4 levels was observed in metastatic tumor cells." (PMID 40075679, 2025). "By inhibiting CDK4/6 activity, these agents induce cell cycle arrest, and reduce tumor cell proliferation." (PMID 40649034, 2025). "CDK4/6 activation facilitates the transition from G1 to S phase and confers tumor cells with the capability to effectively suppress cellular senescence and apoptosis." (PMID 40083693, 2025). "In pancreatic cancer, mutations frequently occur in the TGF‐β receptor, leading to the sustained activation of CDK4/6 in tumour cells." (PMID 40525649, 2025). "Preclinical studies demonstrate that CDK4/6i treatment markedly enhances the efficacy of PD-1/PD-L1 checkpoint inhibitors, primarily by augmenting the immunogenicity of tumor cells." (PMID 41550427, 2025). "A recent report from our institutional LIBERATE cohort study, which included 51 patients with HR+/HER2− MBC receiving standard ET and CDK4/6i evaluated ctDNA detection and dynamics using a high-sensitivity tumor-informed assay." (PMID 41226406, 2025). "The miR-34a is a key regulator of tumor suppression controlling the expression of several targets involved in the cell cycle (c-MYC, E2F, CDK4 and CDK6), apoptosis (BCL2 and SIRT1) and tumor-associated invasion (c-MET)." (PMID 40755967, 2025). "In accordance with these data, CDK4/6 inhibitors were able to reverse a tumour immunosuppressive status in ER-positive/HER2-negative metastatic breast cancer patients." (PMID 41388212, 2025). "Their results suggested that in vitro, the CDK4/CDK6 inhibited fibroblasts can induce genotype-dependent tumor cell proliferation and prolonged inhibition of senescent cells in the TME." (PMID 40075679, 2025). "Studies supported that CDK4/6 inhibitors enhance tumor antigen presentation by macrophages and dendritic cells." (PMID 40856900, 2025). "While oncogenic pathways like HER2 and cyclin D1/CDK4 have been extensively characterised in BC, the roles of tumour suppressor genes, particularly those modulating chemotherapy response, remain understudied." (PMID 40564026, 2025). "A well-documented effect of CDK4/6 inhibitors is the induction of tumor cell senescence, which depends on RB and FOXM11 activity." (PMID 39800748, 2025). "In vivo assays using xenograft tumor models in mice further demonstrated that reduced tumor growth and enhanced sensitivity to Tam and Abema caused by silencing of KIFC2 were partially reversed by CDK4 overexpression." (PMID 40299549, 2025). "In preclinical models of HPV-negative HNSCC, CDK4/6 inhibition decreased tumor growth and in combination with cetuximab, synergistically reduced viability of cell lines." (PMID 41018114, 2025). "We also observed that MEN1-KD induced a strong reduction of the menin, Ki67, CDK2, and CDK4 expression in the xenografted tumor tissues, suggesting that menin is an oncogenic factor in BLCA cells in vivo." (PMID 40837414, 2025).
tumor (continued). "For context, Cyclin D1 is an allosteric master regulator of the cell cycle, more specifically it works in concert with the activating cyclin-dependent kinases (CDK4/6) to allow for G1/S checkpoint progression 50,51 and hence tumour growth." (PMID 40765817, 2025). "The CDK4/6 inhibitor ribociclib holds promise in cancer therapy but how cell cycle inhibitory drugs affect the anti-tumor immune response remains a question." (PMID 40032842, 2025). "For instance, EGFR amplifications activate PI3K/AKT signaling to fuel tumor growth, while CDK4 gains bypass cell cycle checkpoints, and RB1 losses impair homologous recombination repair." (PMID 40636690, 2025). "While early-stage genetic profiles are generally considered invariant during metastasis, recent evidence suggests that tumor cells can acquire an E2F: OFF state through CDK4/6 inhibition." (PMID 40017494, 2025). "As RB is frequently lost in TNBC tumor samples, CDK4/6 inhibitors are generally thought to be ineffective against these cancers." (PMID 40836337, 2025). "Tertiary lymphoid structures and higher tumor-infiltrating lymphocytes also showed favorable survival trends in the CDK4/6i arm." (PMID 40017494, 2025). "For this type of tumor, a combination of endocrine therapy and a CDK4/6 inhibitor serves as the standard of care in advanced or metastatic cases." (PMID 40227585, 2025). "We also sought to explore the tumor intrinsic role of RB activation in modulating the immune landscape of TNBC to differentiate from the systemic effects imparted by treatment with CDK4/6 inhibitors." (PMID 41326426, 2025). "Some studies with CDK4/6 inhibitors suggest the potential to slow disease progression or control tumor growth in bone metastasis sites, specifically within the subgroup of patients with bone metastases from the overall patient population." (PMID 40005476, 2025). "Early studies have shown that combining the MEK inhibitor trametinib with the CDK4/6 inhibitor palbociclib (T/P) enhances anti-tumor effects by inducing tumor cell senescence through Rb and activating NK cells." (PMID 40149983, 2025). "Anti-tumor effects can be achieved by inhibiting CDK4/6, which stops cells in the G1 phase and prevents cell mitosis." (PMID 40134916, 2025). "Dysregulated activation of the cyclin-dependent kinase 4 and 6 (CDK4/6) and cyclin D1 regulatory complex is known to drive the cell cycle and tumor progression, especially in HPV-unrelated HNSCC." (PMID 41018114, 2025). "Conversely, loss of Ser41 phosphorylation by CDK4/6 inhibition or Ser41A mutation, promotes YAP1 degradation and suppresses YAP1‐driven tumor progression." (PMID 39968498, 2025). "This reduction in immune cell proliferation complicates the balance between enhancing anti-tumor immunity and managing the toxic effects of CDK4/6 inhibitors." (PMID 39930131, 2025). "Here, we investigated the effects of cell cycle pathway activation on the TME and ICB response and elucidated mechanisms underlying the optimized sequential combination of CDK4/6i and ICB using syngeneic tumor models." (PMID 40936164, 2025). "Clarifying the molecular mechanism by which CDK4/6is regulate immunity and determining how their anti-tumor effects can be enhanced to mitigate adverse events are urgent issues that need to be addressed." (PMID 41463246, 2025). "In the present study, we aimed to evaluate the synergistic effects of combining RT with CDK4/6 inhibitors and anti-PD-L1 antibodies on tumor suppression in vivo using 4T1 and EMT6 immunocompetent mouse models." (PMID 40836337, 2025). "Preclinical evidence indicates that CDK4/6is exert anti-tumor effects by acting on malignant cells and on diverse immune cells within the microenvironment." (PMID 41463246, 2025). "Meanwhile, unexpected effects have emerged from the real-world use of CDK4/6 inhibitors, including their impact on cell metabolism, autophagy, and the tumour microenvironment." (PMID 40563591, 2025).
tumor (continued). "Given the variety of available therapies, data from the clinical practice setting are crucial for informing clinical decisions after tumor progression during ET plus CDK4/6i therapy." (PMID 39982725, 2025). "Previous research has indicated that CDK4/6 inhibitors not only exert effects on the cell cycle but also have regulatory roles in tumor immunity, although the research findings are controversial." (PMID 41463246, 2025). "Even after the tumor had acquired chemoresistance in this patient, dual CDK4/6 inhibition in combination with Ganetespib impaired organoid viability better than single treatment." (PMID 40204953, 2025). "Palbociclib, a selective inhibitor of the cyclin-dependent kinases CDK4 and CDK6, was found to enrich tumor organoids with RB1 mutations." (PMID 40507353, 2025). "Chemotherapy, radiotherapy, and targeted therapeutic drugs, including CDK4/6is, can all induce tumor cell senescence." (PMID 41463246, 2025). "Results from recent clinical trials (RIBECCA, POP and MONALEESA 2/3/7) and in vivo model studies indicate that immune interactions also play an important but complex role in determining tumor response to CDK4/6 inhibition." (PMID 40032842, 2025). "Preclinical data indicated that CDK4/6 inhibitors enhance the tumor cell antigen presentation capacity and restrict the proliferation of immunosuppressive regulatory T-cells." (PMID 40856900, 2025). "We next assessed protein expression levels of KIFC2, USP9X, and CDK4 in 45 tumor samples from patients with HR+/HER2– BC by IHC." (PMID 40299549, 2025). "The single cell transcriptomic approach also enabled us to identify distinct gene expression profiles in tumor and non-tumor cells, providing insights into the mechanisms that drive early versus late disease progression on CDK4/6is." (PMID 39955556, 2025). "This study explored the combination of RT with CDK4/6 inhibitors to improve TNBC immunotherapy by modulating the tumor microenvironment." (PMID 40836337, 2025). "As molecularly targeted agents, CDK4/6i are administered to patients with specific tumor biological profiles, primarily HR+/HER2− disease and preserved Rb function." (PMID 41514594, 2025). "CDK4/6 inhibitors exert effective anti-tumor effects by blocking the cell cycle and, as a result, have become vital in the systemic treatment of malignant tumors." (PMID 41463246, 2025). "It is worth noting that palbociclib is the first CDK4/6-selective cycle inhibitor to demonstrate broad-ranging efficacy in many tumor types." (PMID 41560755, 2025). "This nanoplatform halts the tumor cell cycle by inhibiting cyclin-dependent kinase 4, but also uses PDT, activated by laser irradiation, to facilitate the release of tumor antigens and attract dendritic cells." (PMID 40391023, 2025). "Although both CDK4/6i priming regimens led to remarkable increases in T cell infiltration, we observed significantly slower tumor growth, and even regression, in C‐P‐treated tumor‐bearing mice compared with the C‐PC treatment group." (PMID 40936164, 2025). "These contrasting findings suggest that the effect of CDK4/6 inhibitors on PD-L1 expression depends on the tumor context, the signaling pathways involved, or the CDK4/6 inhibitor used." (PMID 39930131, 2025). "First, a CDK4/6 inhibitor activated the expression of endogenous retroviral elements in tumor cells and increased intracellular levels of double-strand DNA." (PMID 40862837, 2025). "In tumor tissue, the expression levels of miR-124 targets, including CDK4 and CDK6, were reduced in UMSCs expressing miR-124 group." (PMID 40134003, 2025). "For instance, CDK4 inhibition sensitizes tumor cells to DNA-damaging agents by restoring cell cycle checkpoints and allowing more effective engagement of apoptotic pathways." (PMID 40076599, 2025). "CDK4/6 inhibitors induce tumor cell cycle arrest and synergistically promote antitumor immune responses." (PMID 38856753, 2024).